TRIM56 (tripartite motif containing 56)
Diseases named in the same sentence as TRIM56 in open-access papers (continued):
Sharing a sentence is not in itself a finding about the gene and the disease.
glioma (continued). "To examine the effects of TRIM56 on glioma cell function, we first performed gene set enrichment analysis (GSEA) based on the TCGA and CGGA_mRNAseq_325 datasets." (PMID 36870986, 2023). "Considering the role of TRIM56 in glioma malignancy, its prognostic value was further assessed in both CGGA_mRNAseq_325 and TCGA cohorts." (PMID 36870986, 2023). "We also developed a mouse xenograft glioma model through the intracranial transplantation of TRIM56-NC and TRIM56-OE U87 cells in nude mice." (PMID 36870986, 2023). "ROC curves and area under curve (AUC) values also demonstrated the accuracy of TRIM56 in predicting the 1-, 3-, and 5-year OS of glioma, LGG, and GBM patients in CGGA_mRNAseq_325 and TCGA cohorts." (PMID 36870986, 2023). "Considering that the differentially expressed genes regulated by TRIM56 knockdown were highly enriched in the Rho GTPase signaling and the motility-promoting effect of TRIM56 on glioma cells, we further assessed the effect of TRIM56 on CDC42 activation." (PMID 36870986, 2023). "Taken together, these results demonstrated that the positive effect of TRIM56 on glioma cell motility is mediated via CDC42 activation." (PMID 36870986, 2023). "In vitro and in vivo experimental studies revealed that TRIM56 promoted the migration and invasion of glioma cells." (PMID 36870986, 2023). "The 3D spheroid-based invasion assays of glioma stem cells also revealed that knockdown of CDC42 or treatment with the CDC42 specific inhibitor ZCL278 inhibited the invasion-promoting effect of TRIM56 in glioma cells." (PMID 36870986, 2023). "TRIM56 overexpression promoted the invasive ability of glioma stem cells, while TRIM56 knockdown suppressed it." (PMID 36870986, 2023). "To further investigate the regulatory role of TRIM56 in glioma cell migration and invasion, we performed 3D spheroid-based invasion assays using TRIM56 knockdown and overexpressing glioma stem cells." (PMID 36870986, 2023). "Taken together, these results suggest that TRIM56 expression in gliomas is significantly increased and that this high expression significantly correlates with malignant phenotypes and a poor prognosis." (PMID 36870986, 2023). "To investigate which functional domains of TRIM56 interact with cIAP1, we transfected cIAP1 with various deletion mutants of TRIM56 into glioma cell lines and performed co-IPs." (PMID 36471347, 2022). "We observed elevated expression of TRIM56 in malignant gliomas and revealed that TRIM56 promoted glioma progression in vitro and in a GBM xenograft model in nude mice." (PMID 36471347, 2022). "Overexpression of TRIM56 decreased the number of cells in G0/G1 in glioma and enhanced the colony forming ability relative to controls." (PMID 36471347, 2022). "In conclusion, our study revealed a TRIM56-cIAP1 axis that promotes malignant progression in glioma." (PMID 36471347, 2022). "Immunoblot analysis of glioma cell lines transfected with TRIM56 showed reduced levels of polyubiquitinated cIAP1." (PMID 36471347, 2022). "cIAP1 rescued the cell cycle parameters and the clonogenic ability of glioma cells with TRIM56 knocked down." (PMID 36471347, 2022). "Taken together, we demonstrated that TRIM56 promoted the malignant behavior of glioma cells by enhancing the stability of cIAP1 protein." (PMID 36471347, 2022). "We found that TRIM56 is the most highly elevated TRIM family member in clinical specimens and associated with higher grade and poorer clinical prognosis in gliomas." (PMID 36471347, 2022). "In conclusion, these results suggested that cIAP1 is a potential substrate for TRIM56, involved in the malignant proliferation and invasion of glioma cells." (PMID 36471347, 2022). "In summary, while knockdown of TRIM56 suppressed malignant behavior, overexpression of TRIM56 promoted proliferation and migration of glioma cells in vitro." (PMID 36471347, 2022).
glioma (continued). "In summary, we demonstrated that TRIM56 is elevated in human gliomas and knockdown of the protein inhibits tumor growth in an orthotopic GBM xenograft model in mice." (PMID 36471347, 2022). "To further investigate the function of TRIM56 in glioma development, we performed RNA-seq analysis on LN229-sh-TRIM56 and LN229 control cells." (PMID 36471347, 2022). "To begin to explore the role of TRIM56 in human glioma, we knocked down expression of TRIM56 in human glioma cell lines GBM#P3, LN229 and U118MG with two independent short hairpin RNAs (shRNA)." (PMID 36471347, 2022). "TRIM56 is expressed in a variety of cell types, including immune cells, glial cells and tumor cells, and more highly expressed in glioma cells." (PMID 36471347, 2022). "Overall, the results further demonstrated a role for TRIM56 as an oncogene in the development of human glioma." (PMID 36471347, 2022). "Additionally, we further demonstrated overexpression of TRIM56 promoted glioma progression under in vivo conditions by tumor xenograft model." (PMID 38348047, 2024). "In addition, the spearman method was used to calculate the correlation between TRIM56 expression level and immune checkpoint inclusion in gliomas." (PMID 38348047, 2024). "TRIM56 expression was most closely related to M2 macrophages in glioma." (PMID 38348047, 2024). "To further evaluate the prognostic value of TRIM56 high expression tumor cells in glioma, we used the “Findmarkers” function in the R package “Seurat” to obtain marker gene sets of TRIM56 high expression subgroups with logFC greater than 1 and corrected p value less than 0.05 as screening criteria." (PMID 38348047, 2024). "By comparing the changes of macrophage markers in glioma tissues, we further confirmed that overexpression of TRIM56 may affect the glioma immunosuppressive microenvironment by regulating macrophage polarization." (PMID 38348047, 2024). "In addition, we verified the expression level of TRIM56 in different grades of gliomas by immunohistochemistry (IHC) of human glioma tissues, and the results showed that TRIM56 protein expression was higher in high-grade gliomas." (PMID 38348047, 2024). "We also used univariate and multivariate Cox regression to determine whether TRIM56 expression could serve as an independent prognostic factor in gliomas." (PMID 38348047, 2024). "However, the role of TRIM56 in tumors is still unclear, and its expression and functional changes in gliomas are rarely reported." (PMID 38348047, 2024). "Furthermore, the detection of TRIM56 expression in various glioma cell lines was conducted via Western blot analysis, revealing that the expression levels of TRIM56 were significantly elevated in glioma cell lines compared to normal human astrocytes." (PMID 38348047, 2024). "In order to clarify the relationship between TRIM56 expression and immune infiltration-related cells, using CIBERSORT and ssGSEA algorithms, we can find that TRIM56 has a significant correlation with M2 macrophages in glioma, which is significantly correlated with poor prognosis of glioma." (PMID 38348047, 2024). "This study illustrates the molecular characteristics of TRIM56 in the progression of glioma to a certain extent, and reveals the expression of immune molecules and their corresponding functional changes during the progression of glioma." (PMID 38348047, 2024). "We found that TRIM56 expression was directly regulated by SP1, and TRIM56 enhanced glioma cell migration and invasion via activation of CDC42, which was mediated through the interaction of TRIM56 with IQGAP1 to increase the K48-K63-linked ubiquitination transition of IQGAP1." (PMID 36870986, 2023). "TRIM47 promotes the proliferation, migration, and invasion of glioma cells, while the role of TRIM56 in gliomas remains unclear." (PMID 36870986, 2023). "Furthermore, the glioma cell invasion and cancer cell invasion gene sets were significantly enriched in the TRIM56 high-expression glioma group." (PMID 36870986, 2023).
glioma (continued). "Interestingly, we observed a broader and more jagged tumor edge in the TRIM56-OE xenograft glioma model than in TRIM56-NC model, indicating that TRIM56 overexpression enhanced the invasive potential of glioma cells in vivo." (PMID 36870986, 2023). "Given that the diffuse invasiveness of glioma is closely related to chemoradiotherapy resistance, TRIM56 may represent a promising therapeutic target in glioma." (PMID 36870986, 2023). "Considering the vital role of the IQGAP1-CDC42 pathway in cellular migration and invasion, inquiry into the TRIM56-IQGAP1 axis in glioma may open avenues for the development of novel therapeutic strategies." (PMID 36870986, 2023). "However, the specific role of TRIM56 and the potential mechanism through which it promotes tumor progression in glioma remain incompletely understood." (PMID 36870986, 2023). "Furthermore, IHC staining of glioma specimens revealed an increase in the invasive ability of glioma cells with an increase in TRIM56 expression." (PMID 36870986, 2023). "Mechanistically, TRIM56 was found to interact with IQGAP1 to promote its K63-linked ubiquitination and inhibit degradative K48-linked ubiquitination at Lys-1230, thus promoting CDC42 activation in glioma cells." (PMID 36870986, 2023). "In conclusion, our study provides insights into the mechanisms through which TRIM56 promotes glioma motility, i.e., by regulating IQGAP1 ubiquitination to promote CDC42 activation, which might be clinically targeted for the treatment of glioma." (PMID 36870986, 2023). "Taken together, these data indicate that TRIM56 promotes glioma cell migration and invasion." (PMID 36870986, 2023). "Thus, cIAP1 rescued the invasive ability of glioma cells that had been suppressed due to TRIM56 knockdown." (PMID 36471347, 2022). "TRIM56-regulated post-translational modifications may contribute to glioma development through stabilization of cIAP1." (PMID 36471347, 2022). "The findings suggest that TRIM56-regulated post-translational modifications may contribute to glioma development through stabilization of cIAP1 and that TRIM56 may serve as a novel prognostic indicator and therapeutic molecular target for GBM." (PMID 36471347, 2022). "In addition, we queried the CGGA database for correlation between expression patterns of TRIM56 and clinical parameters and/or specific molecular subtypes of glioma." (PMID 36471347, 2022). "A xenograft animal model was used to verify the tumor promoting effect of TRIM56 on glioma in vivo." (PMID 36471347, 2022). "TRIM56 expression was low in normal brain tissue, but increased with increasing grade of glioma." (PMID 36471347, 2022). "Finally, images of immunofluorescence staining acquired with confocal microscopy showed that TRIM56 co-localized with cIAP1 in human gliomas, normal brain tissue samples and GBM cells." (PMID 36471347, 2022). "TRIM56 also showed prognostic significance in overall survival of glioma patients." (PMID 36471347, 2022). "TRIM56 potentially promotes glioma development as a deubiquitinating enzyme of the apoptosis inhibitor cIAP1, thereby stabilizing the protein, inhibiting glioma cell apoptosis and promoting glioma cell proliferation." (PMID 36471347, 2022). "To determine whether protein levels were correspondingly increased, we performed immunohistochemistry (IHC) for TRIM56 on an independent cohort of glioma (n = 18) and normal brain tissue samples (n = 3)." (PMID 36471347, 2022). "TRIM56 regulation of cell cycle was detected by flow cytometry, and the results showed that overexpression of TRIM56 significantly increased the percentage of cells in S phase and G2/M phase, suggesting that overexpression of TRIM56 promotes the proliferation of glioma cells." (PMID 38348047, 2024). "Moreover, we used ESTIMATE methods were used to investigate the relationship between TRIM56 expression and the purity of tumor tissue, we could find that TRIM56 in glioma was significantly negatively correlated with tumor purity." (PMID 38348047, 2024).
glioma (continued). "Therefore, we further analyzed the expression and prognostic characteristics of TRIM56 in gliomas." (PMID 36870986, 2023). "In addition, TRIM56 expression was significantly different among glioma subtypes (IDH-wild type vs. IDH-mutant, MGMT promoter methylated vs. MGMT promoter unmethylated, and Chromosome 1p19q codeletion vs. Chromosome 1p19q non-codeletion) in the CGGA_mRNAseq_325 and TCGA databases." (PMID 36870986, 2023). "The data together indicated that TRIM56 might function as an oncogene in human gliomas." (PMID 36471347, 2022). "Since TRIM56 knockdown significantly downregulated cIAP1 expression and cIAP1 has been documented to play an oncogenic role in a variety of cancers, we hypothesized that cIAP1 may be a key molecule mediating the malignant function of TRIM56 in gliomas." (PMID 36471347, 2022). "Thus, TRIM56 or proteins downstream of TRIM56 may be new targets to investigate for the diagnosis and treatment of human glioma." (PMID 36471347, 2022). "In contrast, E3 ligase TRIM56 is transcriptionally upregulated by SP1 and impacts IQGAP1-CDC42 signaling to facilitate glioma migration and invasion." (PMID 37723588, 2023). "Therefore, targeting TRIM56 may represent a potential therapeutic approach for glioma treatment." (PMID 36870986, 2023). "The TRIM56 protein expression was also higher in high-grade gliomas, IDH wild-type gliomas and no 1p/19q codeletion gliomas." (PMID 38348047, 2024). "Utilizing RNA-seq data from CGGA and TCGA, TRIM56 expression was significantly increased in IDH wild-type gliomas and gliomas without 1p/19q co-deletion." (PMID 38348047, 2024). "To explore whether TRIM56 promoted glioma cell motility by regulating CDC42 activation, we carried out Transwell chamber migration and invasion assays on glioma cells under TRIM56 overexpression and CDC42 knockdown conditions." (PMID 36870986, 2023). "In glioma, TRIM56 does not function as an E3 ligase but as a deubiquitinating enzyme to stabilize the expression of apoptosis inhibitor cIAP1, thereby promoting glioma progression." (PMID 36902478, 2023). "Herein, we found that expression of the tripartite motif containing 56 (TRIM56), a RING-finger domain containing E3 ubiquitin ligase, was markedly higher in glioma than in normal brain tissue, and was significantly correlated with malignant phenotypes and a poor prognosis." (PMID 36870986, 2023). "As TRIM56 has been revealed to promote radiotherapy tolerance in gliomas, our finding that SP1 drives TRIM56 transcription provides evidence for the mechanism through which SP1 promotes glioma radiotherapy resistance." (PMID 36870986, 2023). "We found that TRIM56 expression was directly transcriptionally regulated by SP1, which has not been addressed in previous studies on the role of TRIM56 in glioma." (PMID 36870986, 2023). "Although previous studies have put forth that TRIM56 can suppress the radio-sensitization of GBM by regulating the FOXM1-mediated DNA repair, the function of TRIM56 in glioma has not been sufficiently studied." (PMID 36870986, 2023). "Other studies on the role of TRIM56 in glioma only focused on the functional domain where TRIM56 plays a role, without clarifying the ubiquitination sites of downstream proteins regulated by TRIM56." (PMID 36870986, 2023). "In addition, immunohistochemical (IHC) staining and Western blot analyses of clinical glioma tissue samples revealed a strong positive correlation between SP1 and TRIM56 expression." (PMID 36870986, 2023). "We found that TRIM56 expression was highly upregulated in gliomas compared to normal brain tissue and that increased TRIM56 expression was positively correlated with increasing grade." (PMID 36471347, 2022). "In this study, we demonstrated that TRIM56 is upregulated in human glioma and functions not as a ubiquitin ligase in glioma, but as a deubiquitinating enzyme to stabilize the expression of the apoptosis inhibitor cIAP1." (PMID 36471347, 2022).
glioma (continued). "Furthermore, we utilized single-cell analysis to investigate the impact of TRIM56 expression on cell communication between glioma cells and non-tumor cells." (PMID 38348047, 2024). "OS analysis showed that high expression of TRIM56 in glioma indicated a significant poor prognosis of patients, which could not help but arouse our curiosity whether TRIM56 is a new immune marker in glioma." (PMID 38348047, 2024). "Interestingly, TRIM56 in gliomas function as deubiquitinating enzymes rather than E3 ligases." (PMID 36902478, 2023). "In order to investigate the molecular expression pattern of TRIM56, we evaluated the expression levels of TRIM56 in IDH wild-type (WT) and IDH mutant (Mut) gliomas and in 1p/19q co-deletion and without 1p/19q co-deletion." (PMID 38348047, 2024).
breast cancer (6 papers, 2013 to 2024). A primary or metastatic malignant neoplasm involving the breast. "The expression of TRIM56 is positively correlated with ERα and PR in breast cancer samples and is associated with poor prognosis in patients treated with endocrine therapy." (PMID 36902478, 2023). "Here we report that the RING family ubiquitin ligase TRIM56 associates with and stabilizes ER alpha protein in the cytoplasm in breast cancer cells, which subsequently leads to increased estrogen signaling activity and cell proliferation in vitro and in vivo." (PMID 31000690, 2019). "In conclusion, our study reveals an interesting posttranslational mechanism between TRIM56 and ER alpha in breast cancer progression." (PMID 31000690, 2019). "Since ER alpha signaling is predominant in ER-alpha-positive breast cancer cells, we did further analysis on ER alpha target genes expression change by TRIM56 depletion." (PMID 31000690, 2019). "In order to investigate the potential role of TRIM56 in breast cancer cells, TRIM56 was depleted in MCF-7 and T47D cells." (PMID 31000690, 2019). "TRIM56 depletion significantly decreases ER alpha signaling activity and ER-alpha-positive breast cancer proliferation in vitro and in vivo." (PMID 31000690, 2019). "TRIM56 expression is positively correlated with ER alpha and PR in breast cancer samples and is related to poor prognosis in endocrine therapy patients." (PMID 31000690, 2019). "Our study reveals a novel modulation of TRIM56 in controlling ER alpha ubiquitination and stability, which subsequently modulates ER alpha target gene expression and ER-alpha-positive breast cancer progression." (PMID 31000690, 2019). "In our study, we identify the E3 ubiquitin ligase TRIM56 as the novel modulator of ER alpha signaling in breast cancer." (PMID 31000690, 2019). "To approach the function of TRIM56 in breast cancer cells in an unbiased way, we depleted TRIM56 in MCF-7 breast cancer cells for the whole genomic expression analysis." (PMID 31000690, 2019). "The knockdown of TRIM56 enhances the proliferation and metastasis of breast cancer cells." (PMID 36902478, 2023). "Furthermore, TRIM56 has been shown to be an oncogene in lung and breast cancers, but a tumor suppressor in acute myeloid leukemia (AML)." (PMID 36471347, 2022). "In the study, we examine the role of TRIM56 in ER-alpha-positive breast cancer cells." (PMID 31000690, 2019). "Targeting TRIM56 could be a promising approach for ER-alpha-positive breast cancer." (PMID 31000690, 2019). "In all, targeting TRIM56 could be a promising therapeutic strategy for breast cancer treatment." (PMID 31000690, 2019). "Our previous research demonstrated that SMURF1, TRIM56 and RNF181 can interact with ERα and enhance breast cancer growth." (PMID 39215346, 2024). "In breast cancer, TRIM11 and TRIM56 confer ERα stability, whereas TRIM8 increases ERα degradation in the cytoplasm." (PMID 35498431, 2022). "Besides, TRIM56 overexpression could further facilitate both MCF-7 cell proliferation and normal epithelial breast cancer cell proliferation." (PMID 31000690, 2019).